FOXP3 (forkhead box P3)
Diseases named in the same sentence as FOXP3 in open-access papers (continued):
Sharing a sentence is not in itself a finding about the gene and the disease.
lung adenocarcinoma (40 papers, 2009 to 2025). A carcinoma that arises from the lung and is characterized by the presence of malignant glandular epithelial cells. "In stage I lung adenocarcinoma, a high density of FOXP3+ TIL was also associated with shorter recurrence-free probability." (PMID 30153850, 2018). "Previously, we reported high FoxP3+/CD3+ lymphocyte ratio as an independent risk factor of recurrence in stage I lung adenocarcinoma." (PMID 26318038, 2015). "In our current study, we demonstrated that FoxP3+ regulatory T lymphocyte infiltration was positively associated with ERα expression in lung adenocarcinoma." (PMID 26318038, 2015). "In summary, this small, retrospective pilot suggests that higher FOXP3, PD 1, and CD32B (relative to CD8 or CD19) levels are associated with adverse pathological features and shorter DFS in resectable lung adenocarcinoma." (PMID 41375087, 2025). "FOXP3 has been found to express abnormally in lung squamous cell carcinoma and lung adenocarcinoma, suggesting that this gene plays an oncogene role." (PMID 38674427, 2024). "In another study, the remarkable FOXP3 overexpression in lung adenocarcinoma specimens (N = 40) was confirmed by immunohistochemical (IHC) staining." (PMID 38674427, 2024). "It was worth noting that FOXP3 is highly expressed in lung squamous cell carcinoma (P < .001) and lung adenocarcinoma (P < .001) compared with normal tissues, suggesting that FOXP3 plays an oncogene role in pan cancer." (PMID 36550816, 2022). "We initially investigated the role of forkhead box protein P3-positive (Foxp3+) regulatory T cells (Tregs) in EGFR-mutant lung adenocarcinomas." (PMID 34494649, 2021). "Here, we found that PD-L1 expression on VECs determined CD8+ T cells’, FoxP3+ T cells’ infiltration, and the prognosis of patients with lung adenocarcinoma." (PMID 32366856, 2020). "KDM3A is suggested to aid lung adenocarcinoma cells in evading the immune system of patients by upregulating forkhead box P3 (Foxp3) expression in regulatory T cells (Tregs)." (PMID 32354028, 2020). "Immunohistochemical staining of GRP94 in human lung adenocarcinoma (AD) and corresponding normal tissue was performed, and its relationship with FOXP3+ regulatory T‐cell (Treg) infiltration analyzed." (PMID 31970893, 2020). "Upregulation of TLR4 significantly increases the expression of KDM3A in A549 lung adenocarcinoma cells, which subsequently controls Foxp3 transcription." (PMID 32354028, 2020). "We evaluated the correlation between immunoreactivity of α-smooth muscle actin (α-SMA), a well-known marker of CAFs, and subpopulations of tumour-infiltrating lymphocytes determined by CD3, CD4, CD8, and Foxp3, in 27 lung adenocarcinoma tissues." (PMID 31462002, 2019). "Using tissue microarray and immunohistochemistry, Suzuki and colleagues found that tumor interleukin-12 receptor β2 (IL-12Rβ2), IL-7R, and stromal FoxP3/CD3 ratio are independent predictors of recurrence in patients with stage I lung adenocarcinoma." (PMID 25950176, 2015). "In A/J mice inoculated with lung adenocarcinoma cells resistant to rapamycin, antibody-mediated depletion of Foxp3+ cells reduced lung tumorigenesis by 80%." (PMID 19330036, 2009). "Furthermore, an elevated presence of tumor-infiltrating CD4+ FOXP3+ Tregs has been described in patients with the 'mesenchymal' lung adenocarcinoma phenotype in comparison to those with an 'epithelial' lung adenocarcinoma phenotype." (PMID 41023740, 2025). "In NSCLC, whether it is lung squamous cell carcinoma (P < .001) or lung adenocarcinoma (P < .001), FOXP3 is highly expressed in cancer tissue compared with normal tissue." (PMID 36550816, 2022). "FOXP3+/CD4+ cell ratio can be used to predict the prognosis of lung adenocarcinoma." (PMID 36385958, 2022).
lung adenocarcinoma (continued). "The TIMER database analysis was obtained, in lung adenocarcinoma, the expression of FOXP3 was inversely correlated with the purity of the tumor (r = −0.476, P = 2.79E−29); FOXP3 expression was positively correlated with the infiltration of common humoral immunity B cells (R = 0.531, P = 1.36E−36)." (PMID 36550816, 2022). "Our finding is supported by the studies reported by others, demonstrating that the overexpression of FOXP3 decreases mouse Lewis lung cancer cell sensitivity to chemotherapy and that the ectopic expression of FOXP3 promotes cell growth, migration and invasion in lung adenocarcinoma." (PMID 28716029, 2017). "They suggested that FOXP3 might be considered a cisplatin resistance gene of lung adenocarcinoma." (PMID 36235242, 2022). "Additionally, there was further research focused on the regulation of FOXP3 in lung adenocarcinoma." (PMID 36235242, 2022). "However, a detailed analysis of the immunophenotype of lymphocytes infiltrating the lung adenocarcinoma tissue in stage I showed that a high density of FoxP3 (Forkhead Box P3)-positive lymphocytes and high stromal FoxP3+ cells/CD3+ cells ratio was a strong predictor of recurrence." (PMID 34502043, 2021). "In conclusion, this study highlights the prognostic significance of FOXP3, PD-1, and CD32B expression in resectable lung adenocarcinoma, emphasizing their combined impact on patient survival outcomes." (PMID 41375087, 2025). "In lung adenocarcinoma, Foxp3 upregulates CCND1 (a gene of cell cycle G1/s checkpoint); thereby enhancing lung adenocarcinoma." (PMID 35326661, 2022). "Here, we evaluated the infiltration of lung adenocarcinoma CD3+ T cell, CD4+ T cell, CD8+ T cell, Foxp3+ T cell, and their matched normal tissues." (PMID 34484468, 2021). "The literature suggests that the FoxP3:CD3 ratio in the tumor matrix, as well as expression levels of IL-12 and IL-17, is markedly correlated with post-operative recurrence in early lung adenocarcinoma." (PMID 31921619, 2019). "Growth of TC1 lung adenocarcinomas was impaired in PCAF−/− mice compared to WT mice, in conjunction with decreased infiltration by CD4+Foxp3+ Treg cells but increased infiltration by host CD8 T cells." (PMID 31003455, 2019). "The findings from this study highlight the significant role that immune markers, such as FOXP3, PD-1, and CD32B, play in the tumor microenvironment (TME) of lung adenocarcinoma, providing valuable insights into their potential as prognostic biomarkers and therapeutic targets." (PMID 41375087, 2025). "This team also revealed a positive correlation between tumor-derived FOXP3 and lung adenocarcinoma TNM stage, and FOXP3 could inhibit the chemosensitivity to cisplatin." (PMID 36235242, 2022). "Therefore, in order to investigating the role of TMSB10 in TAMs of lung adenocarcinoma, we isolated the tumor-infiltrating immune cells in xenograft tumors, and found that CSF1R+ TAMs and Foxp3+ Tregs were reduced in TMSB10 knockdown group." (PMID 33349268, 2020). "In three vasculature-rich tumors (lung, colon, and kidney cancers), we found that VECs with overexpression of PD-L1 were concomitantly with higher infiltration of FoxP3+ Treg cells (r = 0.348, P = 0.026), but with lower infiltration of CD8+ T cells (r = −0.398, P = 0.010) in lung adenocarcinomas." (PMID 32366856, 2020). "For example, in lung adenocarcinoma in mice, it was demonstrated that the bacteria Diaphorobacter nitroreducens, when combined with oxaliplatin, increased the number of CD163- and CD68-positive macrophages while reducing Treg cells (CD4 FOXP3), thus slowing tumor progression." (PMID 40075568, 2025). "We found that the expression level of FOXP3 was significantly lower in the PCBP1-AS1 high expression group than in the PCBP1-AS1 low expression group, indicating that PCBP1-AS1 expression was negatively correlated with the degree of Treg cell infiltration in lung adenocarcinoma." (PMID 38433921, 2024).
lung adenocarcinoma (continued). "Because long-term depletion of lung-associated Foxp3+ cells by anti-CD25 antibodies was not achievable, we developed a short-term assay, and performed a series of studies using syngeneic lung adenocarcinoma cell lines derived from NNK-induced tumors in A/J mice." (PMID 19330036, 2009). "Contrary to our expectations, α-SMA-positive CAFs in lung adenocarcinoma were by no means correlated with lymphocyte subtypes evaluated by CD3, CD4, CD8, and Foxp3 immunohistochemistry." (PMID 31462002, 2019).
allergic asthma (39 papers, 2010 to 2025). A asthma with a basis in a pathological type I hypersensitivity reaction. "Later, Lu and collaborators demonstrated that increased expression of Foxp3 on Treg cells by the injection of lentiviral particles carrying the Foxp3 gene in an OVA-induced allergic asthma model caused the reduction of pulmonary NKT cells." (PMID 38629075, 2024). "The unbalance between pro-inflammatory and anti-inflammatory cytokines associated to Th2/Th1/Treg cells is also closely linked gene expression for STAT6, T-bet, and Foxp3 in allergic asthma." (PMID 36685604, 2022). "Impaired tolerance to innocuous particles during allergic asthma has been linked to increased plasticity of FoxP3+ regulatory T cells (Tregs) reprogramming into pathogenic effector cells, thus exacerbating airway disease." (PMID 32931477, 2020). "Imbalance in TH17/Tregs, elevated IL-17, and IL-4 response and downregulation of FOXP3 were associated with allergic asthma." (PMID 24995020, 2014). "In the context of allergic asthma models, an increase in Foxp3 expression correlates with reduced airway inflammation." (PMID 40870825, 2025). "For instance, targeted delivery of chemically modified Foxp3 mRNA to sites of inflammation in the house dust mite-induced allergic asthma served as a safe and efficient therapeutic tool by regulating T cell immune responses." (PMID 36601108, 2022). "We found that the proportion of CD25+Foxp3+CD127- Treg cells in the peripheral blood of patients with allergic asthma was lower than in those of healthy subjects." (PMID 34497608, 2021). "TGF-β is important in the generation of antigen-specific FoxP3+ Tregs, and its abrogation in vivo leads to uncontrolled Th2 allergic asthma." (PMID 32931477, 2020). "The populations of Th17 cells (CD4+ RORγt+ IL17z+) and Tregs (CD4+ CD25+ Foxp3+) among peripheral PBMCs were examined using flow cytometry for both the allergic asthma and healthy control groups." (PMID 32834826, 2020). "Our studies partly contrast earlier findings, which showed a reprogramming of FoxP3+ Tregs into ex-FoxP3 Th2-like cells during HDM-induced allergic asthma." (PMID 32931477, 2020). "Taken together, our findings indicate that IL-4Rα–unresponsive FoxP3+ Tregs result in exaggerated innate Th2-type, IL-33–dependent airway inflammation and a break in tolerance during allergic asthma." (PMID 32931477, 2020). "The increase in TIGIT expression and its attenuation by DW2008S in mice with allergic asthma appear to be limited to FOXP3− effector T cells, which seems to mostly result from fluctuations in number of TIGIT+ IL‐4+ Th2 cells." (PMID 29512870, 2018). "A study describing the increased expression of FOXP3 in patients with allergic asthma relative to non-allergic asthma and Treg cell suppressor capacity observed in both are similar to our findings." (PMID 30233389, 2018). "The results suggest AOS consumption reduces the risk of allergic asthma by increasing the percentage of CD4+CD25+ T cells, CD4+CD25high, CD4+CD25+FoxP3+ Treg cells and CD4+CD25highCD127low Treg cells in PBMCs." (PMID 30294594, 2018). "The current study suggests that resveratrol attenuates allergic asthma by downregulating miR-34a that induces increased expression of FOXP3, a master regulator of Treg development and functions." (PMID 30619345, 2018). "In accordance with our results, previous studies showed the therapeutic potentials of helminths in resistance from allergic asthma via the expansion of CD4+CD25+FOXP3+ regulatory cells and IL-10 and TGF-β production." (PMID 28494800, 2017). "Our findings are in line with previous observations AHR is more sensitive to the presence of lung-resident Foxp3+ regulatory T cells than allergen-specific IgE or airway eosinophilia in experimental mouse models of allergic asthma." (PMID 23393567, 2013).
allergic asthma (continued). "Furthermore, showing higher levels of intracellular IL-17A and RORγ(t), associated with lower levels of Foxp3 in T-lymphocytes, together with higher plasma levels of IL-17A we suggests that there is a Th17/Treg imbalance toward Th17 cells in moderate forms of allergic asthma and rhinitis." (PMID 23573194, 2013). "This shall provide the basis using FOXP3 methylation for in vivo microbial exposure in future field studies assessing childhood pulmonary diseases such as allergic asthma." (PMID 20967272, 2010). "MiR-34a can mediate allergic asthma by increasing forkhead box P3 (FOXP3) expression." (PMID 34234781, 2021). "Therefore, the in vivo role of canonical IL-4 receptor α (IL-4Rα) signaling, an essential driver of Th2-type airway responses to allergens, on the regulatory function of FoxP3+ Tregs in allergic asthma was explored." (PMID 32931477, 2020). "Additionally, TNF-α impairs the regulatory activity of natural Treg cells via the TNF-α receptor 2 (TNFR2) signaling pathway to down-modulate Foxp3 expression in allergic asthma." (PMID 27553600, 2016). "Therefore, we speculated the impact of DMF on the level of anti-inflammatory Foxp3 in the WT or Nrf2fl/flCD4cre mice after inducing OVA-allergic asthma." (PMID 38711519, 2024). "FoxP3 is the master transcription factor required for development towards T regs lineage which through their effector cytokines transforming growth factor‐β and interleukin‐10 suppress inflammation and promote airway remodeling in airway diseases such as allergic asthma." (PMID 32737949, 2020). "In addition, we also assessed whether the beneficial effects of EA on allergic asthma could be correlated with CD4+CD25+Foxp3+ regulatory T cells (Treg)." (PMID 22649477, 2012). "In a mouse model of allergic asthma, suppression of airway inflammation was dependent on both mesenteric CD103+DC and Foxp3+ regulatory T cells (Tregs)." (PMID 38239430, 2023). "Compared with the HC (n = 17) and non-allergic asthma subjects (naAS, n = 5), the percentage and number of CD25+Foxp3+ Treg cells was markedly decreased in patients with allergic asthma (aAS, n = 42)." (PMID 34497608, 2021). "Our results highlight a complex function of IL-4Rα signaling on FoxP3+ Tregs in regulating airway hyperreactivity and lung pathology during HDM-induced allergic asthma." (PMID 32931477, 2020). "AOS can be effective in the treatment of allergic asthma in children by increasing the percentage of CD4+CD25+ T cells, CD4+CD25high, CD4+CD25+FoxP3+ Treg cells, and CD4+CD25highCD127low Treg cells." (PMID 30294594, 2018). "The results suggest that AOS consumption increases the percentage of gated CD4+ T cells, CD4+CD25+ T cells, CD4+CD25high, CD4+CD25+FoxP3+ Treg cells, and CD4+CD25highCD127low Treg cells in children with allergic asthma." (PMID 30294594, 2018). "OVA-induced airway inflammation and Th2-mediated allergic asthma were suppressed by oral oleanolic acid, including by inhibiting the transcription factors GATA-3 and RORγt and promoting the transcription factors T-bet and Foxp3." (PMID 39796399, 2025). "Ultimately, Imuno TF mitigated the allergic asthma due to the restoration of balance between the responses of Th1/Th2 as well as Treg cells, and their respective transcription factors the T-bet/STAT6 and Foxp3." (PMID 36685604, 2022). "However, murine models of allergic asthma as well as asthmatic individuals present high levels of STAT6 in airway, while both genic expression of T-bet and Foxp3 are drastically downregulated in lung tissue." (PMID 36685604, 2022). "The characteristic features of allergic asthma, including airway hyperreactivity, histopathology, cytokines (IL-4, IL-5, IL-13, IL-17, and INF-γ), and CD4+CD25+Foxp3+Treg cells in bronchoalveolar lavage fluid (BALF), and downstream proteins of mTORC1/2 signaling were examined." (PMID 29234390, 2017).
allergic asthma (continued). "However, the role of miRNA in resveratrol-mediated attenuation of allergic asthma, its ability to induce the expression of FOXP3, a master regulator of Tregs and immunosuppression, has not been previously investigated." (PMID 30619345, 2018). "It was already described that IL-10 production by thymic Foxp3-negative Treg cells alleviates the lung eosinophil infiltration, globet cell hyperplasia and IgE and production in mice subjected to the OVA model of allergic asthma." (PMID 31805682, 2019). "However, the number of MLN FOXP3+ Tregs, including TIGIT+ Tregs, in the mice with allergic asthma did not increase compared to the number in the normal mice." (PMID 29512870, 2018).